OSGIN2 (oxidative stress induced growth inhibitor family member 2)
Description:
Monooxygenase catalytic activity (By similarity). May be involved in meiosis or the maturation of germ cells.
Synonyms: C8orf1; hT41
Tractability: PROTAC: ubiquitination databases record sites on it.
Gene: Protein-coding gene on chromosome 8 (89,901,849 to 89,927,888, forward strand). Ensembl gene ENSG00000164823.
Subcellular location: Midbody
Subcellular location (Human Protein Atlas): Nucleoli
Gene Ontology:
Molecular function: growth factor activity
Biological process: negative regulation of cell growth; signal transduction
Cellular component: midbody
Genetic constraint (gnomAD): Loss-of-function variants: 8 observed, 31.8 expected, observed/expected ratio (o/e) 0.25, 90% interval 0.15 to 0.45. The upper end of that interval is the gene's LOEUF score, 0.45, which puts it in group 2 of 6, group 1 being the genes least tolerant of losing a copy. Missense variants: 400 observed, 531.87 expected, observed/expected ratio (o/e) 0.75, 90% interval 0.69 to 0.82. Synonymous variants: 177 observed, 192.75 expected, observed/expected ratio (o/e) 0.92, 90% interval 0.81 to 1.04.
Homologues: Orthologues: chimpanzee OSGIN2 (99% identical), macaque OSGIN2 (98% identical), dog OSGIN2 (95% identical), pig OSGIN2 (95% identical), mouse Osgin2 (92% identical), rat Osgin2 (90% identical), guinea pig OSGIN2 (89% identical), rabbit OSGIN2 (88% identical), tropical clawed frog osgin2 (65% identical), zebrafish osgin2 (55% identical), Caenorhabditis elegans osgn-1 (24% identical). Paralogues in human: OSGIN1 (43% identical).
Diseases named in the same sentence as OSGIN2 in open-access papers:
OSGIN2 is named in the same sentence as 12 diseases in open-access papers, as found by Europe PMC text mining. Sharing a sentence is not in itself a finding about the gene and the disease. The quoted sentences say what the papers report.
colorectal cancer (3 papers, 2022 to 2025). A primary or metastatic malignant neoplasm that affects the colon or rectum. "Osgin2 was one of these OXEGs used in the prognostic model, with consistent upregulation in many of the colorectal cancer tumors." (PMID 40149945, 2025). "However, Osgin2 genes have been utilized in creating prognostic models for colorectal cancer survival spans." (PMID 40149945, 2025).
Nijmegen breakage syndrome (3 papers, 2022 to 2025). Nijmegen breakage syndrome is a rare genetic disease presenting at birth with microcephaly, dysmorphic facial features, becoming more noticeable with age, growth delay, and later-onset complications such as malignancies and infections. "Osgin2 is associated with bone marrow loss, specifically in Nijmegen breakage syndrome and retinitis pigmentosa type 62." (PMID 40149945, 2025). "Furthermore, OSGIN2 is associated with Nijmegen Breakage Syndrome, and skeletal disorder has been known as one of its main phenotypes." (PMID 35729522, 2022). "Oxidative stress-induced growth inhibitor family member 2(OSGIN2), also named C8orf1/HT41, regions on chromosome 8q21.3 and adjacent to the gene for Nijmegen breakage syndrome." (PMID 37031243, 2023).
gastric cancer (2 papers, 2023 to 2025). A primary or metastatic malignant neoplasm involving the stomach. "To address the correlation between OSGIN2 mutation and cancer progression, we evaluated the frequency of mutations in OSGIN2 in gastric cancer." (PMID 37031243, 2023). "Our study confirmed the association of OSGIN2 with gastric cancer and suggested it as a potential marker for the diagnosis and prognosis of GC by bioinformatics analysis and experimental validation." (PMID 37031243, 2023). "The potential relationship between OSGIN2 expression, prognosis, functional enrichment of associated differential genes, immune infiltration, and mutational information in gastric cancer were comprehensively investigated using bioinformatics analysis." (PMID 37031243, 2023). "The cBioPortal database was utilized to evaluate the mutation frequency of OSGIN2 in gastric cancer." (PMID 37031243, 2023). "The results showed that gastric carcinoma cells and tissues contained high levels of OSGIN2, which was associated with a poor prognosis for GC patients." (PMID 37031243, 2023). "For instance, in gastric cancer cells, knockdown of Osgin2 inhibited tumor cell proliferation and increased the number of cells stuck between the G2/M phases of the cell cycle." (PMID 40149945, 2025). "Further characterization of the role of Osgin2 in gastric cancer revealed that gastric carcinoma cells and tissues contain high levels of OSGIN-2." (PMID 40149945, 2025). "Knockout of Osgin2 in gastric cancer cells via siRNA transfection led to cell cycle arrest and inhibited tumor proliferation." (PMID 40149945, 2025). "OSGIN2 was significantly highly expressed in gastric cancer and was able to serve as a predictor of prognosis." (PMID 37031243, 2023). "In our research, the upregulated of OSGIN2 was found in various cancers, including gastric cancer, glioblastoma, and pancreatic cancer." (PMID 37031243, 2023). "In the comparison of OSGIN2 mRNA expression levels in 5 kinds of gastric cancer cells and 1 normal gastric epithelial cell, gastric cancer cells also displayed a significantly higher level." (PMID 37031243, 2023). "Through the comparing of OSGIN2 expression between tumors and the corresponding normal tissues in TCGA, the results demonstrated the increased expression level of OSGIN2 in various tumor tissues, including the gastric cancer group." (PMID 37031243, 2023). "Paired sample analysis of gastric cancer and normal tissues also showed high OSGIN2 expression in gastric cancer tissues." (PMID 37031243, 2023). "Immunohistochemical results from the HPA public database showed that OSGIN2 was higher expressed in gastric cancer tissues compared with normal tissues." (PMID 37031243, 2023). "In addition, the high expression of OSGIN2 in different gastric cancer microarray data suggested a poor prognosis." (PMID 37031243, 2023). "Moreover, the OSGIN2 expression level in gastric cancer was increased in all stages I-IV compared with normal tissues." (PMID 37031243, 2023). "Finally, we conducted functional experiments to validate the promoting effect of OSGIN2 on gastric cancer cells." (PMID 37031243, 2023). "Thus, high expression of OSGIN2 in gastric cancer may affect tumor immunity and lead to carcinogenesis." (PMID 37031243, 2023). "This study explored the promoting effect of oxidative stress-induced growth inhibitor family member 2(OSGIN2) on gastric cancer (GC) through public databases and in vitro experiments." (PMID 37031243, 2023). "Therefore, we thought OSGIN2 might be an important biomarker for gastric cancer diagnosis, prognosis, and even one of the key factors involved in tumor progression." (PMID 37031243, 2023). "In the three different gastric cancer microarray data from the KM database, the high expression of OSGIN2 decreased the survival time and affected the prognosis of GC patients." (PMID 37031243, 2023).
gastric cancer (continued). "To this end, we compared OSGIN2 expression in gastric cancer and normal tissues using the TCGA and HPA datasets, and analyzed the clinical relevance between differences in OSGIN2 expression and prognosis in gastric cancer by the Kaplan–Meier plot database." (PMID 37031243, 2023).
osteoporosis (2 papers, 2022 to 2025). A condition of reduced bone mass, with decreased cortical thickness and a decrease in the number and size of the trabeculae of cancellous bone (but normal chemical composition), resulting in increased fracture incidence. "Osgin2 has also been implicated in the development of osteoporosis in rat jawbone models." (PMID 40149945, 2025). "Infusion of anti-OSGIN2 ameliorated osteoporotic jawbone loss and improved the bone formation, which verified the role of OSGIN2 in osteoporosis." (PMID 35729522, 2022). "Oxidative stress is redundant in osteoporosis, which results in up-regulation of OSGIN2." (PMID 35729522, 2022). "In this study, we investigated the mechanism that OSGIN2 responded to oxidative stress and affected osteogenesis of jawbone BMSCs via regulating RORα/BSP-OCN during osteoporosis." (PMID 35729522, 2022).
ovarian carcinoma (1 paper, 2022). A malignant neoplasm originating from the surface ovarian epithelium. "We also found that the copy number of OSGIN2, and NBN differed in RIPK2-altered and RIPK2-unaltered patients, and these genes were coexpressed with RIPK2 in ovarian cancer." (PMID 35477477, 2022).
tumor (3 papers, 2021 to 2025). "In addition, we explored the role of OSGIN2 in cell cycle regulation, and the results suggested that OSGIN2 knockdown would cause DNA damage in tumor cells and an increase in cells stuck in the G2/M phase." (PMID 37031243, 2023). "Knockdown of OSGIN2 inhibited tumor cell proliferation and contributed to cell cycle arrest." (PMID 37031243, 2023). "Thus, while this study provides insight into the link between miRNA regulation of stress genes implicated in tumorigenesis in a hypoxic environment, the mechanism relating Osgin2 to tumor hypoxia is not yet understood." (PMID 40149945, 2025).
cancer (2 papers, 2023 to 2025). A tumor composed of atypical neoplastic, often pleomorphic cells that invade other tissues. "Our study demonstrated that OSGIN2 may be functionally linked to cancer formation and development, and suggested upstream and downstream genes that may be related." (PMID 37031243, 2023). "The current literature shows that Osgin1 and Osgin2 display differential expression in a variety of cancers and diseases, though this is, in most cases, the extent of clinical knowledge." (PMID 40149945, 2025). "In comparison with Osgin1, much less research has been performed elucidating the mechanistic role of Osgin2 in cancer." (PMID 40149945, 2025). "Overall, correlational experiments illustrate that Osgin1 and Osgin2 are differentially expressed across a wide range of pathologies, including many types of cancer, infections, chronic conditions, and various other disorders." (PMID 40149945, 2025). "While the majority of research implicating the Osgin genes in disease focuses mainly on their roles in cancers, Osgin1 and Osgin2 have also been abnormally expressed in a wide variety of conditions and disorders." (PMID 40149945, 2025). "Pan-cancer analysis revealed that most of the current clinical immune-related biomarkers, including PD-L1 and CTLA4, were associated with OSGIN2." (PMID 37031243, 2023). "Similar upregulation of Osgin2 was observed bioinformatically in other cancers." (PMID 40149945, 2025). "Researches have shown that OSGIN2 may be involved in the physiological processes of cancer and other diseases." (PMID 37031243, 2023). "However, there is speculation that OSGIN2 may be involved in cancer development." (PMID 37031243, 2023).
skeletal diseases (1 paper, 2022). "OSGIN2, an oxidative stress induced factor, has been found to be associated with skeletal diseases." (PMID 35729522, 2022).
OSGIN2 also shares sentences with these, for which no sentence is quoted: clear-cell adenocarcinoma of (1 paper); glioblastoma (1); pancreatic cancer (1); retinitis pigmentosa type 62 (1).